CCDC30 (coiled-coil domain containing 30)
Synonyms: PFDN6L; FLJ20972; PFD6L; LOC728621
Tractability: No criterion of Open Targets' tractability assessment is met for any kind of drug.
Gene: Protein-coding gene on chromosome 1 (42,463,221 to 42,657,190, forward strand). Ensembl gene ENSG00000186409.
Genetic constraint (gnomAD): Loss-of-function variants: 45 observed, 63.4 expected, observed/expected ratio (o/e) 0.71, 90% interval 0.56 to 0.91. The upper end of that interval is the gene's LOEUF score, 0.91, which puts it in group 3 of 6, group 1 being the genes least tolerant of losing a copy. Missense variants: 455 observed, 552.95 expected, observed/expected ratio (o/e) 0.82, 90% interval 0.76 to 0.89. Synonymous variants: 178 observed, 193.17 expected, observed/expected ratio (o/e) 0.92, 90% interval 0.81 to 1.04.
Homologues: Orthologues: macaque CCDC30 (86% identical), chimpanzee CCDC30 (83% identical), rabbit CCDC30 (67% identical), mouse Ccdc30 (46% identical), rat Ccdc30 (42% identical), dog CCDC30 (40% identical).
Diseases named in the same sentence as CCDC30 in open-access papers:
CCDC30 is named in the same sentence as 5 diseases in open-access papers, as found by Europe PMC text mining. Sharing a sentence is not in itself a finding about the gene and the disease. The quoted sentences say what the papers report.
cancer (2 papers, 2021 to 2025). A tumor composed of atypical neoplastic, often pleomorphic cells that invade other tissues. "Also, several genes of cancer suppressors were activated after mitochondrial administration, including Csad, Ccdc30, Macrod1, Pcdh1, Tprkb, and Hdac11." (PMID 34131403, 2021).
CCDC30 also shares sentences with these, for which no sentence is quoted: tumor (2 papers); hepatocellular carcinoma (1); liver cancer (1); thymoma (1).